BRD4 (bromodomain containing 4)
Diseases named in the same sentence as BRD4 in open-access papers (continued):
Sharing a sentence is not in itself a finding about the gene and the disease.
HIV-1 infection (4 papers, 2017 to 2025). The type species of lentivirus and the etiologic agent of acquired immunodeficiency syndrome (AIDS). "For example, BRD4 (bromodomain containing 4), an inhibitor gene of HIV-1 infection, has 11 known transcript isoforms." (PMID 28910283, 2017). "In T cells with latent HIV-1 infection, we could detect the binding of BRD4 to HIV-1 LTR by ChIP-PCR." (PMID 40726975, 2025). "Some studies suggest that BRD4 competes with Tat for binding PTEF-b during active transcription and that its over-expression may inhibit HIV-1 infection." (PMID 38581045, 2024). "Analogous to HIV-1 Tat, the cellular bromodomain-containing protein 4 (BRD4) recruits p-TEFb to cellular promoters to exert control at a transcription elongation step, with Tat thought to compete with BRD4 for p-TEFb binding during HIV-1 infection." (PMID 37676006, 2023).
Hyperglycemia (4 papers, 2022 to 2025). An increased concentration of glucose in the blood. "Reported mechanistic benefits of inhibiting the action of BRD4 in hyperglycaemia conditions are associated with increased caveolin‐1 expression, reduced AKT phosphorylation and most recently, activation of PINK1/Parkin‐mediated mitophagy." (PMID 40831067, 2025). "This study explored hyperglycemia-induced proliferation and migration of GC cells, and the underlying involvement of the Pin1/BRD4 signal pathway, both in vitro and in vivo." (PMID 35461311, 2022). "The role and underlying mechanism of the Pin1/BRD4 axis in hyperglycemia-induced proliferation and migration of GC cells were analyzed in vivo and in vitro." (PMID 35461311, 2022). "In summary, we revealed the critical role of Pin1/BRD4 axis in the association between hyperglycemia and GC." (PMID 35461311, 2022). "This reduction might be subject to both direct effects from Brd4 deficiency during embryonic and adult stages and secondary effects from glucotoxicity due to long‐term hyperglycemia in light of the phenotypic changes in the acute knockout model." (PMID 40539402, 2025). "In summary, hyperglycemia-induced Pin1/BRD4 axis promoted gastric tumorigenicity and tumor metastasis by facilitating NAP1L1 and repressing P21 in vivo." (PMID 35461311, 2022). "In vivo studies indicated that hyperglycemia promotes tumor growth and lung metastasis by inducing Pin1 and BRD4 expression." (PMID 35461311, 2022). "Inhibition of BRD4 through JQ1 treatment in the DM + JQ1 group significantly inhibited tumor growth induced by hyperglycemia in hyperglycemic mice." (PMID 35461311, 2022). "Inhibition of Pin1 or BRD4 significantly inhibited pulmonary metastasis induced by hyperglycemia." (PMID 35461311, 2022). "However, whether hyperglycemia promotes high Pin1 expression in tumor tissues, leading to increased BRD4 expression and tumor cell proliferation, remains unclear." (PMID 35461311, 2022). "Thus, Pin1/BRD4 plays an important role in hyperglycemia-promoted tumor growth." (PMID 35461311, 2022).
ischemic stroke (4 papers, 2020 to 2024). A stroke disorder caused by obstruction of blood flow to the brain, due to thrombotic (local blood clot formation) or embolic (due to a blood clot or other material traveling from another site) event. "Our data further advances our understanding of the protective role of BRD4 degradation by dBET1 in ischemic stroke." (PMID 35761277, 2022). "In models of respiratory infection, vascular inflammation, and ischemic stroke, BRD4 inhibition reduced neutrophil infiltration at the site of injury as measured by immunohistochemical analysis." (PMID 33348732, 2020). "The findings of the present study suggested that CK2 may control BRD4 phosphorylation to regulate fibrotic scar formation, to affecting outcomes after ischemic stroke." (PMID 38381246, 2024). "Our present data demonstrate that CK2 may control BRD4 phosphorylation to regulate fibrotic scar formation and affect outcomes after ischemic stroke." (PMID 38381246, 2024).
latent infection (4 papers, 2013 to 2025). "Further, mLANA K224A/K228A/K229A bound BRD4 normally, yet vmLANAK224A/K228A/K229A was deficient for latent infection." (PMID 24146618, 2013). "In both cases, it depends on BRD4: disrupting E2:BRD4 with a dominant-negative BRD4 C-terminal peptide blocks the transactivation function of many PV E2 proteins; conversely, BRD4 knockdown reduces E2’s ability to repress genes that regulate the transition between lytic and latent infection." (PMID 36298829, 2022).
malignant peripheral nerve sheath tumor (4 papers, 2016 to 2022). Malignant peripheral nerve sheath tumor (MPNST) is a rare and often aggressive soft tissue sarcoma occurring in a wide range of anatomical sites. "Studies showed that JQ1 or BRD4 knockdown in NF1 (Neurofibromatosis type 1)-associated malignant peripheral nerve sheath tumors decreased the expression of CCND1." (PMID 26830473, 2016). "Malignant peripheral nerve sheath tumor with PRC2 loss-of-function was sensitive to BRD4 inhibitor, suggesting a promising therapeutic approach of SL-based BRD4 inhibition." (PMID 35918352, 2022). "Interestingly, a previously published study demonstrated that cotargeting of BRD4 and MAPK signaling promoted cell death in a NF1 loss-of-function mouse model of malignant peripheral nerve sheath tumor (MPNST)." (PMID 32960816, 2020).
rhabdoid tumor (4 papers, 2017 to 2025). An aggressive malignant embryonal neoplasm usually occurring during childhood. "Additionally, combing LDC0000167 with the BRD4 inhibitors-JQ1 or iBET-762 against malignant rhabdoid tumors, down-regulated the anti-apoptotic genes MCL-1, BCL-6 and BTG1 as well as MYC and inhibited cell-proliferation and tumor growth in vitro and in vivo." (PMID 34062779, 2021). "PROTACs targeting BRD4 and BRD9, components of the SWI/SNF (BAF) remodelling complex, have also shown efficacy in preclinical MPNST, malignant rhabdoid tumour and synovial sarcoma models." (PMID 40983796, 2025). "In this study, we demonstrate anti-proliferative effects and induction of apoptosis by a combined treatment with BRD4- and CDK9 inhibitors in malignant rhabdoid tumors." (PMID 29156698, 2017).
Stroke (4 papers, 2020 to 2023). Sudden impairment of blood flow to a part of the brain due to occlusion or rupture of an artery to the brain. "The longer observation timepoints could help to demonstrate the efficacy of dBET1 on stroke and further elucidate the underlying neuroprotection mechanisms of BRD4 degradation by dBET1." (PMID 35761277, 2022). "Consequently, BRD4 blockade has attracted increasing interest for associated neurological diseases, including stroke." (PMID 35761277, 2022). "Stroke induced by tMCAO led to a dramatic reduction in BRD4 protein expression level at 48 h after surgery." (PMID 35761277, 2022). "Considering that the global loss of BRD4 is lethal in mice, dBET1 studies help identify in vivo BRD4 protein function and its contribution to stroke." (PMID 35761277, 2022). "A recent study also suggested that inhibition of Brd4 is beneficial for the improvement of neurological deficits induced by stroke." (PMID 32982695, 2020). "However, the understanding of BRD4’s cellular functions and its relevance in diseases such as stroke remains limited, delaying advancements in translating therapeutic strategies targeting BRD4 to the clinic." (PMID 35761277, 2022). "The interaction between BRD4 protein and the NF-κB pathway will be explored in our near future study, which will further elucidate BRD4-dependent molecular mechanisms contributing to neurovascular damage in stroke." (PMID 35761277, 2022). "Furthermore, Brd4 inhibition has been shown to reduce blood–brain barrier damage and stroke volume, improving sensory and motor function after stroke." (PMID 32982695, 2020). "In this study, using a transient focal cerebral ischemia mouse model, we hypothesized that BRD4 degrader dBET1 elicits robust neuroprotective efficacy against stroke damage by mechanisms involving regulating inflammatory and oxidative processes along with preserving BBB integrity." (PMID 35761277, 2022). "In addition, dBET1 treated mice also exhibited lower protein level of BRD4 under stroke condition." (PMID 35761277, 2022). "Bromodomain-containing protein 4 (BRD4), a member of the bromodomain and extra-terminal domain (BET) protein family, plays a crucial role in regulating inflammation and oxidative stress that are tightly related to stroke development and progression." (PMID 35761277, 2022).
Thrombocytopenia (4 papers, 2021 to 2025). A reduction in the number of circulating thrombocytes. "Moreover, since BRD4 is expressed in most tissues, toxicity (most commonly thrombocytopenia) also limits the efficacy of BETi in the treatment." (PMID 36936659, 2023). "The thrombocytopenia and anemia associated with fedratinib may be related to its on-target inhibition of WT JAK2 and off-target inhibition of FMS-like tyrosine kinase 3 (FLT3) and bromodomain-containing protein 4 (BRD4)." (PMID 35903543, 2022). "Unfortunately, BET inhibitors are not selective to BRD4 alone, and the pharmacokinetic profiles of many BET inhibitors failed tremendously in the initial phases of clinical trials due to dose-limiting toxicities such as thrombocytopenia." (PMID 41278204, 2025).
acute promyelocytic leukemia (3 papers, 2019 to 2026). An aggressive form of acute myeloid leukemia (AML), characterized by arrest of leukocyte differentiation at the promyelocyte stage, due to a specific chromosomal translocation t(15;17) in myeloid cells. "Additionally, the co-expression of BRD4 and PD-L1 was associated with poor OS in non-acute promyelocytic leukemia patients with intermediate/high risk or under 60 years." (PMID 33658927, 2020). "Mechanistically, the epigenetic readers like bromodomain-containing protein 4-dependent (BRD4-dependent) super enhancers (SEs) activate proinflammatory genes, including promyelocytic leukemia (PML)." (PMID 41842990, 2026).
adenoid cystic carcinoma (3 papers, 2021 to 2025). A malignant tumor arising from the epithelial cells. "Adenoid cystic carcinoma organoid studies revealed the superior efficacy of proteolysis-targeting chimera dBET6 (targeting Bromodomain-Containing Protein 4 [BRD4]) when compared to conventional inhibitor JQ1, particularly in myoepithelial-rich tumors." (PMID 41425705, 2025). "For example, JQ1, a BET inhibitor, broke up super-enhancers by inhibiting BRD4 and deregulating MYB transcription, consequently inhibiting adenoid cystic carcinoma growth." (PMID 34054916, 2021).
alcoholic liver diseases (3 papers, 2020 to 2025). A disorder caused by damage to the liver parenchyma due to alcohol consumption. "Our study reveals for the first time that the expression level of BRD4 is dramatically up‐regulated in alcoholic liver disease." (PMID 32596881, 2020). "Furthermore, BRD4 can repress antifibrotic factors; in alcoholic liver disease, BRD4 binding to the SIRT1 promoter suppresses SIRT1 expression, which leads to impaired autophagy and heightened TGF-β signaling." (PMID 40149956, 2025). "Therefore, the BRD4/HMGB1 pathway is involved in alcohol‐induced liver injury, and manipulation of this pathway through strategies such as SAA treatment holds great therapeutic potential for the treatment of alcoholic liver diseases." (PMID 32596881, 2020).
chronic kidney disease (3 papers, 2016 to 2022). Impairment of the renal function secondary to chronic kidney damage persisting for three or more months. "This suggests that Brd4 may play an essential role in mediating the progression of chronic kidney disease." (PMID 27732564, 2016).
CNS embryonal tumor (3 papers, 2023 to 2025). "Here, we report a pediatric case of a novel tumor type among the other CNS embryonal tumors classified within the methylation class “CNS Embryonal Tumor with BRD4–LEUTX Fusion”." (PMID 36934287, 2023). "One of these reports characterized the fusion in a large series of pediatric cancers, while the other incorporated detailed clinical and pathological data, including methylome analysis matching to the novel Heidelberg version 12 classifier class “CNS embryonal tumor with BRD4::LEUTX fusion”." (PMID 38500181, 2024). "Finally, using the Heidelberg DNA-methylation classifier, the case was classified as “CNS Embryonal Tumor with BRD4:LEUTX Fusion” (with a calibrated score (cs) of 0.99)." (PMID 36934287, 2023). "Here, we report a pediatric case of a novel tumor type among the other CNS embryonal tumors classified within the methylation class (MC) “CNS Embryonal Tumor with BRD4:LEUTX Fusion” (calibrated score (cs): 0.99) which is not yet integrated into the CNS WHO classification." (PMID 36934287, 2023).
dementia (3 papers, 2021 to 2025). Loss of intellectual abilities interfering with an individual's social and occupational functions. "Through in vitro experimentation, we simulated a natural mutation of Brd4 in dementia patients and observed a decrease in the intensity of cell competition among neural stem cells, thereby implicating it in the pathogenesis of the disease." (PMID 39010274, 2024). "The 23rd and 24th ranked genes, ARMCX6 and BRD4, were linked to impairments in cognition and memory, which are regarded as the common symptoms of dementia." (PMID 34492068, 2021). "Additionally, dementia patients exhibited higher levels of Sparc and low levels of Brd4, and mice carrying the Brd4 mutations that are present in these patients show impairments in neural stem cell competition." (PMID 41440031, 2025). "Our investigation revealed a positive association between dementia and cell competitive negatively‐regulated protein Sparc, as well as a negative association between dementia and cell competitive positively‐regulated protein Brd4." (PMID 39010274, 2024).
head and neck cancer (3 papers, 2020 to 2025). A primary or metastatic malignant neoplasm affecting the head and neck. "The widely-used BRD4 inhibitor JQ1 significantly decreased populations of CSCs in vitro and in vivo by targeting the BRD4-mediated transcriptions at SEs in head and neck cancer (HNSCC)." (PMID 39090713, 2024).
hepatoblastoma (3 papers, 2016 to 2024). Hepatoblastoma (HB) is a malignant hepatic tumor and is the most common pediatric liver cancer. "It has also been shown that the co-culture of hepatoblastoma cells with macrophages induced IL-34 overexpression in cancer cells via BRD4 signaling, further supporting the role of BRD4 in the control of IL-34 expression." (PMID 39451216, 2024). "We next examined if IL‐34 in hepatoblastoma cells was regulated by Brd4 by using the Brd4 inhibitor, JQ‐1." (PMID 35132816, 2022). "Our in vitro study using hepatoblastoma cell lines and HMDMs showed that direct contact with macrophages induced tumor cell proliferation and Brd4 expression, which induced IL‐34 expression." (PMID 35132816, 2022). "In conclusion, a high density of CD163‐positive TAMs was seen in embryonal components of hepatoblastoma cases, and Brd4‐induced IL‐34 production was suggested to induce infiltration of TAMs in embryonal components." (PMID 35132816, 2022). "However, the anti‐tumor effects of the Brd4 inhibitor on hepatoblastoma cells were weak in the present study." (PMID 35132816, 2022). "In addition, Brd4 and IL‐34 may be novel markers for embryonal components of hepatoblastoma cases." (PMID 35132816, 2022).
metastatic disease (3 papers, 2012 to 2025). "In this paper, we will discuss that host genetic background on which a tumor arises can significantly alter the biology of the subsequent metastatic disease, and we will focus on the role of Brd4 in regulating metastasis susceptibility." (PMID 22295248, 2012). "Overall, while most alterations overlapped between primary and metastatic tumors, the enrichment of BRD4 in metastatic disease and KIT in primary tumors suggest potentially meaningful differences in progression that should be confirmed in independent datasets." (PMID 41154418, 2025). "To gain further understanding on how bromodomain inhibitors can be refined to target metastatic tumors, we have further characterized the pro-metastatic short isoform of BRD4." (PMID 24260471, 2013). "Detailed characterization of the unique biology of BRD4-SF will lead to improved inhibitors and strategies that are effective against both the primary and metastatic tumors." (PMID 24260471, 2013). "To better understand how these agents might be used to reduce the morbidity and mortality of cancer, which is primarily due to metastatic disease, we characterized the pro-metastatic isoform of BRD4." (PMID 24260471, 2013). "This would suggest that the Brd4 short isoform might be a competitive inhibitor of the longer isoform and that this inhibition would increase the ability of tumors to progress to metastatic disease." (PMID 22295248, 2012). "This is consistent with our findings that the shorter Brd4 isoform promotes metastatic capacity and also that the competitive inhibition of the longer Brd4 isoform would increase the ability of tumors to progress to metastatic disease." (PMID 22295248, 2012). "We, therefore, hypothesized that the lack of I-BET151 efficacy on metastatic disease is the result of greater inhibition of BRD4-LF compared to BRD4-SF, by differential drug accessibility or other isoform-specific biochemical properties." (PMID 24260471, 2013).
metastatic melanoma (3 papers, 2018 to 2024). A melanoma that has spread from its primary site to another anatomic site. "Researchers have reported significant upregulation in levels of epigenetic BRD4 protein in primary and metastatic melanoma tissues, making it an attractive therapeutic target." (PMID 39238805, 2024). "While hyperactivation of MAPK/ERK pathway BRAF mutation results in upregulation of Bromodomain and extraterminal domain proteins like BRD4 in both primary and metastatic melanoma tissues." (PMID 39238805, 2024). "We next performed immunohistochemical analysis of biopsies from 54 patients with genetically diverse metastatic melanoma and confirmed high expression of BRD4 in NRASMut tumors; BRD4 levels were markedly higher than in tumors harboring mutant BRAF or wild‐type for BRAF and NRAS (WT)." (PMID 29650805, 2018).
mucoepidermoid carcinoma (3 papers, 2015 to 2025). A carcinoma morphologically characterized the presence of cuboidal mucous cells, goblet-like mucous cells, squamoid cells, cystic changes, and a fibrotic stromal formation. "In mucoepidermoid carcinoma, overexpression of BRD4 has been linked to tumorigenicity, with research demonstrating that using the BET inhibitor iBET762 to displace BRD4 from chromatin leads to cell-cycle arrest and activation of cellular senescence, as indicated by increased levels of p16ink4." (PMID 40563615, 2025). "The involvement of bromodomain proteins, especially BRD4, has been reported in the progression and therapeutic resistance of squamous-cell carcinoma from the head and neck and mucoepidermoid carcinoma from the salivary glands." (PMID 40563615, 2025).
myocardial ischemia (3 papers, 2023). A disorder of cardiac function caused by insufficient blood flow to the muscle tissue of the heart. "At the same time, studies have shown that miRNA-494-3p plays a protective role in myocardial ischemia‒reperfusion injury by inhibiting BRD4." (PMID 37085803, 2023).